HSF1 (heat shock transcription factor 1)
Diseases named in the same sentence as HSF1 in open-access papers (continued):
Sharing a sentence is not in itself a finding about the gene and the disease.
ovarian carcinoma (26 papers, 2014 to 2025). A malignant neoplasm originating from the surface ovarian epithelium. "Another study revealed that Dickkopf-3 (DKK3), a protein associated with aggressive ovarian cancer, works with HSF1 to control the behavior of cancer-associated fibroblasts (CAFs), which can promote tumor growth and invasion." (PMID 37958341, 2023). "HSF1 expression is associated with poor prognosis and treatment resistance in various malignancies, including breast, prostate, lung, and ovarian cancers." (PMID 37958341, 2023). "Further, phosphorylation of HSF1 at Ser326 in ovarian cancer samples was associated with poor prognosis." (PMID 35311075, 2022). "Sixth, ovarian cancer that responds to external stimuli or stress causes “HSF1 activation” and “cellular response to heat stress”." (PMID 33228226, 2020). "hSF1 expression has been found to be significantly lower in ovarian cancer than in normal ovarian tissue and mutations in NR5A1 are associated with primary ovarian insufficiency." (PMID 31744494, 2019). "Additionally, phosphorylated HSF1, specifically phospho-Ser326, has been identified as a potential marker for HSF1 activity and is associated with poor prognosis in ovarian cancer." (PMID 38339390, 2024). "A genome-wide search identified 8q24 (where HSF1 is situated) as high-risk loci in ovarian cancer." (PMID 35311075, 2022). "HSF1 was also linked to EMT in 3D cell culture model of ovarian carcinoma." (PMID 35311075, 2022). "A pronounced upregulation of HSP70 could also be observed in disulfiram/copper-treated ovarian cancer cells, which was associated with an increased molecular weight (activation by hyperphosphorylation) of its transcription factor HSF1 (heat shock factor 1)." (PMID 25593981, 2014). "We also found that the expression of various HSF1 target genes is dependent on both IER5 and HSF1 in ovarian cancer cells." (PMID 40002205, 2025). "The current study also found a significant number of binding sites for HSF1 and MYC in ovarian cancer cells wherein the binding peaks are overlapping, which would be consistent with previous reports suggesting that HSF1 and MYC form protein complexes with DNA." (PMID 39831777, 2025). "We showed that both IER5 and HSF1 are essential for ovarian cancer cell proliferation in both adherent and suspension conditions." (PMID 40002205, 2025). "Although these studies were not in cancer cells, the current results support that MYC and HSF1 also form a protein complex in ovarian cancer cells and MYC-driven ovarian cancer cells are dependent on HSF1." (PMID 39831777, 2025). "HSF1 has also been reported to induce the epithelial–mesenchymal transition in a spheroid model of ovarian cancer following transforming growth factor-β treatment." (PMID 40002205, 2025). "This inhibitor of HSF1 induced tumor regression in human ovarian adenocarcinoma xenografts and was more effective than carboplatin in inhibiting the proliferation of ovarian cancer cells." (PMID 39682216, 2024). "A recent discovery using the chemical probe bisamide, CCT251236, showed impressive results for HSF1 inhibition and antitumor efficacy in a preclinical model using ovarian cancer cells." (PMID 37153737, 2023). "PGPIPN, a hexapeptide derived from the 63-68 amino acid residue of bovine β-casein 181, reduced the resistance of ovarian cancer cells to cisplatin by affecting the HSF1/HSP70 signaling pathway." (PMID 37153737, 2023). "HSBP1 is a 76-amino-acid protein that binds to heat shock factor 1(HSF1), which can be enhanced through lin28A to regulate the stem-like characteristics of ovarian cancer." (PMID 36276091, 2022). "HSF1 phosphorylation at S326 was closely associated with the maintenance of cancer stem-like cells and a high level of S326 phosphorylation in HSF1 correlated with worse prognosis than a low level in ovarian cancer." (PMID 34239690, 2021).
ovarian carcinoma (continued). "This suggests that PGPIPN enhanced the sensitivity of ovarian cancer cells to DDP partially via reducing the activity of HSF1/HSP70 signaling pathway, thus inducing cell apoptosis and decreasing repairment of DNA damage." (PMID 34539881, 2021). "Immunohistochemical staining using clinical ovarian cancer samples revealed that higher expressions of HSF1 pSer326 was related to poorer prognosis." (PMID 28415561, 2017). "Overall, we conclude that both SKOV3 and HEY cells express HSF1 and respond to heat shock, validating the choice of these two ovarian cancer cell lines for our studies." (PMID 27997575, 2016). "We thus conclude that HSF1 promotes EMT in ovarian cancer 3D spheroids at least in part through regulating the levels of EMT-inducing transcription factors." (PMID 27997575, 2016). "The effects for HSF1 are more striking when cells are grown as 3D spheroids, which more closely mimic the in vivo growth conditions of ovarian cancer." (PMID 27997575, 2016). "In summary, we have identified HSF1 as a critical player in ovarian cancer progression, and have identified EMT as a process that is promoted by HSF1." (PMID 27997575, 2016). "In order to determine the role of HSF1 in ovarian cancer, inducible HSF1 knockdown cell lines were created." (PMID 27997575, 2016). "We have identified HSF1 as a critical player in promoting ovarian cancer tumorigenicity by multiple measures in both SKOV3 and HEY ovarian cancer cells." (PMID 27997575, 2016). "Through mining patient data, we find that HSF1 DNA levels are most highly amplified in ovarian cancer as compared to other cancers, and also that ovarian cancer is one of the top cancer types with amplified HSF1 mRNA levels." (PMID 27997575, 2016). "Here, we have established two ovarian cancer inducible HSF1 knockdown cell lines to study the effect of HSF1 on ovarian cancer." (PMID 27997575, 2016). "We thus have established an effective means of knocking down HSF1 to varying degrees in two different ovarian cancer cell lines." (PMID 27997575, 2016). "Similarly, HSF1 has been shown to be required for cancer cell growth in both in vitro and in vivo models of ovarian cancer." (PMID 40002205, 2025). "Further, since other IER5 family genes (IER2 and IER5L) have also been reported to regulate HSF1 activity, this family of genes may collectively be involved in the progression of ovarian cancer via the HSF1 pathway." (PMID 40002205, 2025). "Finally, we showed that this IER5-HSF1-HSP axis is vital for cancer cell growth: Hsf1 knockdown resulted in reduced ovarian cancer cell (HM-1) proliferation and as well as decreased HSP expression, indicating that IER5 regulates HSPs via HSF1." (PMID 40002205, 2025). "Notably, either depletion of HSF-1 expression or chemical inhibition of its transcriptional activity impaired miR-145-5p tumor suppressor activity and the response to cisplatin in ovarian cancer cell lines incubated at 42 °C." (PMID 37598177, 2023). "Anti-HSF1 antibody detection contributes to the early detection of ovarian cancer." (PMID 37958341, 2023). "As 81% of ovarian cancers express the ERα, resolving the interactions of HSF1 and hormone receptor status could also be clinically important." (PMID 35311075, 2022). "As HSF1 is highly conserved, to explore whether cross-reactivity occurs for potential utility in ovarian cancer animal models, the orthologous murine sequences were identified using the NCBI protein blast, and the corresponding peptides also synthesised." (PMID 34439354, 2021). "Similarly, a nucleotide analog which exhibited anti-cancer effects has been shown to downregulate HSF1 in both pancreatic and ovarian cancer studies." (PMID 34439354, 2021). "Our results also show that the peptide may increase the sensitivity of ovarian cancer cells to DDP by HSF1/HSP70 signaling pathway, but related mechanisms need further research." (PMID 34539881, 2021).
ovarian carcinoma (continued). "In clinical studies, increased HSF1 expression levels are correlated with poor prognosis and advanced metastasis in breast cancer, non-small cell lung cancer, gastric cancer, oesophageal squamous cell cancer, ovarian cancer and others." (PMID 34439354, 2021). "Overall, PGPIPN could reduce the mRNA level of genes associated with HSF1/HSP70 signaling pathways in drug-resistant ovarian cancer cell lines and human primary ovarian cancer cell." (PMID 34539881, 2021). "For example, it was previously reported that ly101-4B reduced the expression of the HSF1 in ovarian cancer cells that could be considered as an additional, and probably independent to the E2F inhibition, anticancer effect." (PMID 29844366, 2018). "We thus sought to study the effect of HSF1 knockdown in ovarian cancer cell lines." (PMID 27997575, 2016). "Interestingly, we find that HSF1 gene duplication is more common in ovarian cancer than in any other cancer type in this database by a large margin." (PMID 27997575, 2016). "Our findings thus add to this data and suggest that HSF1 may be an important therapeutic target for ovarian cancer." (PMID 27997575, 2016). "Therefore, HSF1 deserves further research and development as a promising anticancer strategy for ovarian cancer." (PMID 27997575, 2016). "We then assayed our HSF1 knockdown cell lines to determine whether HSF1 is important for ovarian cancer tumorigenicity." (PMID 27997575, 2016). "These experiments in sum support a role for HSF1 in promoting cell motility in ovarian cancer." (PMID 27997575, 2016). "Therefore, using a 3D ovarian cancer culturing system, we have uncovered a positive effect of HSF1 on the ability of TGFβ to induce EMT genes." (PMID 27997575, 2016). "HSF1 could induce ovarian cancer cell EMT and promote cell migration and invasion." (PMID 30326922, 2018). "To assess the impact of Ier5 knockdown on HSF1 target genes, we analyzed the expression of HSPs in HM-1 and MOV ovarian cancer cells following knockdown." (PMID 40002205, 2025). "The current study is the first to show genome binding patterns for both HSF1 and MYC in co-amplified ovarian cancer cells." (PMID 39831777, 2025). "The results shown that gene MZB1, HSF1, PIK3R4, PSMB9, RSF1 and SPI1were significantly overexpressed in ovarian cancer cells SKOV-3." (PMID 40424327, 2025). "There are several clinical trials investigating HSF1 as a therapeutic target, such as a phase Ib study (NCT05226507) investigating NXP800 in ovarian carcinoma." (PMID 39519208, 2024). "Compared with cells in DDP treatment alone, the protein expression levels of HSF1 and HSP70 in human ovarian cancer cells treated with DDP and PGPIPN together significantly decreased in dose-dependent manner (P<0.05 or P<0.01)." (PMID 34539881, 2021). "This study examined the mRNA expression levels of HSF1, HSP70, MDR1 and ERCC1 by RT‐qPCR in SKOV3, SKOV3/DDP, COC1, COC1/DDP and human primary ovarian cancer cells, of which MDR1 and ERCC1 are important drug-resistance genes." (PMID 34539881, 2021). "Western blotting was used to analyze HSF1, HSP70, MDR1 and ERCC1 proteins, which are related to HSF1/HSP70 signaling pathway in SKOV3, SKOV3/DDP, COC1, COC1/DDP and human primary ovarian cancer cells." (PMID 34539881, 2021). "Compared with cells in DDP treatment alone, the expression levels of HSF1 and HSP70 in human ovarian cancer cells treated with DDP and PGPIPN together significantly decreased in dose-dependent manner." (PMID 34539881, 2021). "Knockdown of HSF1 in SKOV3 and HEY ovarian cancer cell lines attenuates the epithelial-to-mesenchymal transition (EMT) in cells treated with TGFβ, as determined by western blot and quantitative RT-PCR analysis of multiple EMT markers." (PMID 27997575, 2016). "PLK1 protein levels in ovarian cancer cells also seem to correlate with MYC and HSF1 levels." (PMID 39831777, 2025).
ovarian carcinoma (continued). "This suggested that PGPIPN may regulate HSF1/HSP70 signaling pathway activity and following cascade to enhance the sensitivity of ovarian cancer cells to DDP." (PMID 34539881, 2021). "To further explore the role of HSF1 in ovarian cancer EMT, we cultured multicellular spheroids in a non-adherent environment to simulate early avascular tumors." (PMID 27997575, 2016). "Interestingly, while SKOV3 cells contain a similar level of basal and activated HSF1 as compared to normal ovarian epithelial T80 cells, HEY cells express higher levels of HSF1, corresponding to the higher levels of HSF1 expression we identified in ovarian cancer patient databases." (PMID 27997575, 2016). "Therefore, it was speculated that PGPIPN may regulate HSF1/HSP70 signal transduction and alter the expression level or activity of proteins in human ovarian cancer cells, which leads to the reduction of MDR1 and ERCC1 expression, thereby increasing the sensitivity of ovarian cancer cells to DDP." (PMID 34539881, 2021).
multiple myeloma (24 papers, 2013 to 2025). "Clinical trials have demonstrated such efficacy for bortezomib associated with several types of HSP90 or HSF1 inhibitors for multiple myeloma (MM) patients." (PMID 28797244, 2017). "Inhibitors targeting HSF1 have been developed and have shown promising results in cancer therapy, such as myeloma and leukemia." (PMID 40675964, 2025). "PI3K/Akt/GSK3β signaling crosstalks with Hsp70/Hsp90 expression by inducing HSF1 expression in multiple myeloma." (PMID 39936995, 2025). "Bortezomib-induced phosphorylation of HSF1 on Ser326 contributes to multiple myeloma resistance to treatment." (PMID 39433125, 2024). "This decrease is associated with the upregulation of FTO, which targets the heat shock factor 1-heat shock proteins (HSF1-HSPs) pathway, promoting the proliferation, migration, and invasion of multiple myeloma cells." (PMID 39072324, 2024). "Initially, we had thought that this pathway was specific primarily for TNBC and myeloma; however, this work shows that HSF1 and DYRK2 expressions correlate across cell states and therapy responses in diverse cancer types." (PMID 36622366, 2023). "Bortezomib-resistance in myeloma occurs either due to up-regulation of HSF1 activity or due to altered redox homeostasis or, in rare cases, due to accumulation of mutations in key bortezomib-docking sites in proteasome subunit of PSMB5." (PMID 36622366, 2023). "Silencing HSF1 in myeloma cells, as well as selective pharmacological inhibition of HSF1, strongly sensitizes cells to proteasome inhibition." (PMID 35311075, 2022). "This is notably the case in myeloma, where HSF1 inhibition using RNA interference induces apoptosis." (PMID 33808130, 2021). "In multiple myeloma cells, the Akt signaling pathway also stabilizes the expression of HSF-1, thereby controlling constitutive and inducible expression of Hsp70, which is critically dependent on Hsp90 chaperone function." (PMID 32121259, 2020). "We also probed for HSP and HSF1 expression in bortezomib-treated isolated CD138+ cells from four different myeloma patients." (PMID 27487129, 2016). "Our results provide a rationale for targeting HSF1 activation in combination with bortezomib to enhance multiple myeloma treatment efficacy." (PMID 27487129, 2016). "Together, these data provide evidence that in order to enhance the efficacy of proteasome inhibition in myeloma treatment, targeting HSF1 is an effective therapeutic strategy." (PMID 27487129, 2016). "Future studies should explore the role of other HSF1 phosphorylation sites in myeloma beyond serine 326, including sites of constitutive phosphorylation." (PMID 27487129, 2016). "Using human myeloma cell lines and primary myeloma cells belonging to various molecular groups, we tested the efficacy of HSP90, HSP70, and heat shock factor 1 (HSF1) inhibitors alone or associated with current antimyeloma drugs." (PMID 25898974, 2015). "High level of Hsf1 is associated with cancer malignancy and poor prognosis clinically, and there is considerable evidence for the direct involvement of Hsf1 in tumourigenesis in cancers including myeloma." (PMID 24675290, 2014). "Apart from Hsp90 inhibitors, inhibitors against Hsp70, Hsp27 and Hsf1 are still in the early phase of development despite strong evidence of their involvement in myeloma survival." (PMID 24675290, 2014). "Early studies also suggest that inhibition of Hsf1 induces apoptosis in myeloma cells in vitro and reduces tumour growth in vivo, and this is associated with lowered expression of multiple downstream heat shock proteins." (PMID 24675290, 2014). "Silencing of HSF1 sensitized multiple myeloma cells to bortezomib treatment." (PMID 39433125, 2024). "Proteasome-inhibitor resistance is extensively observed in multiple myeloma patients and hence dual targeting of HSF1 and DYRK2 could be an alternative strategy to combat the refractory disease." (PMID 36622366, 2023).
multiple myeloma (continued). "In multiple myeloma, HSF1 expression has been demonstrated to be related to poor prognosis." (PMID 36069792, 2022). "HSF1 is elevated in Hodgkin lymphoma, multiple myeloma, CLL and AML." (PMID 36069792, 2022). "This pro-tumor role of HSF1 has been observed in myeloma and cervical cancer." (PMID 33808130, 2021). "In addition, HSF1 regulates HSPs to maintain the protein balance, thereby inhibiting apoptosis of multiple myeloma cells." (PMID 28482903, 2017). "Here, we show that HSF1 knockdown sensitizes myeloma cells to bortezomib treatment." (PMID 27487129, 2016). "Our deep sequencing and proteomic results suggest in particular that the combination of bortezomib with HSF1 inhibition could be beneficial in myeloma therapy." (PMID 24171104, 2013). "Therefore we focused on targeting HSF1 activation upon proteasome inhibition in myeloma cells." (PMID 27487129, 2016). "A recent study demonstrated heat shock transcription factor 1 (HSF1) as a potential new therapeutic target in multiple myeloma and other studies revealed that nuclear transcription factor-kappa B (NFκB) could be a potential target for drug development in different disease entities." (PMID 25484921, 2014). "In multiple myeloma (MM), FTO has also a pro-metastatic role by targeting HSF1, enhancing HSF1 mRNA stability and translation." (PMID 37369946, 2023). "Bortezomib-treated myeloma cell lines induce a cytoprotective HSR, characterized by HSP induction and HSF1 mediates this response." (PMID 27487129, 2016). "The data presented in this study show that myeloma cells activate the HSR in response to bortezomib and that targeting HSF1 can downregulate the HSR and sensitize cells to bortezomib treatment." (PMID 27487129, 2016). "Inhibition of HSF1 and PERK have also recently been proposed by others as promising therapeutic targets in myeloma and represents a proof of principle for our approach." (PMID 24171104, 2013). "We had previously established DYRK2 as a direct HSF1 phosphorylating kinase and showed that DYRK2 inhibition leads to impediment of the cell cycle via accumulation of proapoptotic factors leading to tumour regression of multiple myeloma and TNBC in vivo." (PMID 36622366, 2023). "Instead of attenuating the bortezomib-induced HSR with multiple HSP inhibitors, we hypothesized that knocking down HSF1 would inhibit bortezomib-induced upregulation of the HSR and sensitize myeloma cells to bortezomib treatment." (PMID 27487129, 2016).